S100A9 (S100 calcium binding protein A9)
Diseases named in the same sentence as S100A9 in open-access papers (continued):
Sharing a sentence is not in itself a finding about the gene and the disease.
gastric cancer (21 papers, 2009 to 2025). A primary or metastatic malignant neoplasm involving the stomach. "Our results suggested S100A9-positive inflammatory cells in gastric cancer tissues are associated with early stage of gastric cancer and good prognosis." (PMID 22838504, 2012). "PRM analysis confirmed the upregulation of S100A8 and S100A9 in saliva from patients with gastric cancer." (PMID 41164825, 2025). "Up-regulation of S100A9 expression was observed in many tumors, including breast, colon, skin, and gastric cancers." (PMID 27191989, 2016). "Another in vitro study conducted on gastric cancer cell line underline that S100A8 and S100A9 expression are associated with a decrease in lymph node metastasis and these proteins can be used as biomarkers in gastric adenocarcinoma." (PMID 25298751, 2014). "In human gastric cancer cell line SNU484, S100A8 and S100A9 inhibition was linked with decreased of invasive and migratory phenotypes of tumoral cells." (PMID 25298751, 2014). "S100A9 expression was correlated with an early stage cancer and a better prognosis in patients with gastric cancer." (PMID 25298751, 2014). "In gastric cancer tissues, both S100A9 and S100A8 proteins were detected in the tumor-infiltrating inflammatory cells, while no S100A8/A9 heterodimer was found in any cases." (PMID 22838504, 2012). "The effect of exogenous S100A9 on motility of gastric cancer cells AGS and BGC-823 was then investigated." (PMID 22838504, 2012). "Our results showed that high S100A9 cell count in gastric cancer tissues was negatively correlated with advanced pathological cancer stages, lymph node metastasis, and tumor invasion." (PMID 22838504, 2012). "The purpose of this study is to investigate S100A9 expression in gastric cancer and explore its role in cancer progression." (PMID 22838504, 2012). "S100A9 was identified as an independent prognostic predictor of overall survival of patients with gastric cancer (P = 0.04)." (PMID 22838504, 2012). "S100A9 was specifically expressed by inflammatory cells such as macrophages and neutrophils in human gastric cancer and gastritis tissues." (PMID 22838504, 2012). "In this study, we used gene expression analysis to compare S100A9 expression in gastric cancer tissues and in the adjacent, ostensibly normal tissues." (PMID 22838504, 2012). "Statistical analysis showed that a high S100A9 cell count (> = 200) per 200x magnification microscopic field in cancer tissues was predictive of early stage gastric cancer." (PMID 22838504, 2012). "In this study, the exogenous S100A9 recombinant protein plays a role in inhibiting the gastric cancer cell line BGC-823 migration and invasion." (PMID 22838504, 2012). "Presence of S100A9-positive inflammatory cells in cancer tissues correlates with an early stage cancer and a better prognosis in patients with gastric cancer." (PMID 22838504, 2012). "S100A9 was specifically expressed in inflammatory cells infiltrating gastric cancer tissues and chronic gastritis tissues." (PMID 22838504, 2012). "Since survival analysis showed significantly different prognosis for gastric cancer patients in different cancer stages, we analyzed the relationship between S100A9-positive inflammatory cells count and patient survival rate." (PMID 22838504, 2012). "S100A9 expression in gastric tissue samples from 177 gastric cancer patients was assessed by immunohistochemistry." (PMID 22838504, 2012). "Taken together, S100A9-positive inflammatory cell count in gastric cancer tissue can be used as a predictor to distinguish early stage and advanced gastric cancer with the cutoff of 200 positive cells/HPF." (PMID 22838504, 2012). "Presence of S100A9-positive inflammatory cells in cancer tissues correlates with a better prognosis in patients with gastric cancer." (PMID 22838504, 2012). "In gastric cancer, gene expression and proteomic analysis demonstrated high expression of S100A9 in the tissue." (PMID 22838504, 2012).
gastric cancer (continued). "Further investigation found that S100A8 distribution in human gastric cancer tissues was similar to S100A9." (PMID 22838504, 2012). "Also, the protein S100A9 is observed, which is known to promote invasion and migration through the p38 mitogen-activated, protein kinase-dependent NF-κB activation in gastric cancer cells." (PMID 35566209, 2022). "Then we tested the prediction power of the S100A9 cell count for tumor stage in gastric cancer." (PMID 22838504, 2012). "Importantly, presence of S100A9-positive inflammatory cells in cancer tissues also correlated with a better prognosis in patients with gastric cancer." (PMID 22838504, 2012). "High expression of S100A9 in the inflammatory cells in gastric cancer tissues may indicate that S100A9 plays an important role in gastric cancer development." (PMID 22838504, 2012). "Since the S100A9-positive inflammatory cell count correlated with less aggressive clinicopathological characteristics, we further tested the direct inhibitory function of recombinant S100A9 on the migration and invasion of gastric cancer cells." (PMID 22838504, 2012). "The differential expression and subcellular localization of S100A9 and S100A8/A9 in various tissues may indicate that only S100A9 plays a role in gastric cancer development." (PMID 22838504, 2012). "Finally, to gain insight into the function of S100A9 in cancer cells, we investigated the effect of the recombinant S100A9 protein on migration and invasion of gastric cancer cells AGS and BGC-823." (PMID 22838504, 2012). "Furthermore, exogenous S100A9 protein inhibited migration and invasion of gastric cancer cells." (PMID 22838504, 2012). "Our findings demonstrate that salivary proteins, particularly S100A8, S100A9, CST4, and CST5, hold significant potential as non-invasive biomarkers for gastric cancer detection." (PMID 41164825, 2025). "It is suggested that S100A8 and S100A9 can activate p38 mitogen-activated protein kinase (MAPK)/nuclear factor kappa B in inflammation and gastric cancer cells invasion." (PMID 35397606, 2022). "Two gastric cancer cell lines, AGS and BGC-823, were treated with serum-free medium or medium containing different concentrations of S100A9 recombinant protein (10, 20, 50 and 100 ng/ml, respectively)." (PMID 22838504, 2012). "In the present study, a subcluster of neutrophils with high-activity phenotypes accounted for a major proportion of PB samples after treatment, which also highly expressed well-known tumor-promoting genes of gastric cancer including MMP9, S100A8, S100A9, PORK2, and TGF-β1." (PMID 37333017, 2023). "The molecular mechanisms of S100A9 in gastric cancer invasion and migration are not fully understood, however." (PMID 27600085, 2016). "Taken together, the differential expression and subcellular localization of S100A9, S100A8 and S100A8/A9 in various tissues may implicate their different roles in gastric cancer or chronic gastritis environment." (PMID 22838504, 2012). "Within these genes, the expression of S100A9 in gastric cancer tissues was higher than that of matched adjacent noncancerous mucosa (P = 0.00241)." (PMID 22838504, 2012). "In this study, we found that S100A9 was specifically located in inflammatory cells infiltrating gastric cancer tissues and chronic gastritis tissues, while all gastric cancer cells or adjacent cells of gastric mucosa did not express S100A9." (PMID 22838504, 2012). "In this study, we used iTRAQ and PRM-based quantitative proteomics to detect four saliva protein biomarkers of gastric cancer, including S100A8, S100A9, NUCB2, and CST4, which make them potential novel biomarkers for the noninvasive diagnosis of GC." (PMID 41164825, 2025). "To confirm this hypothesis, we further investigated the subcellular localization pattern of S100A9, S100A8 and S100A8/A9 heterodimer expression by performing immunofluorecence staining in a tissue microarray including 23 cases of gastric cancer and 57 cases of chronic gastritis." (PMID 22838504, 2012).
gastric cancer (continued). "In addition, the cell count of S100A8, a dimerization partner of S100A9, was not correlated with the clinicopathological features or overall survival in patients with gastric cancer." (PMID 22838504, 2012). "Immunohistochemistry analyses of gastric cancer samples showed that S100A9 was exclusively located in inflammatory cells, such as macrophages and neutrophils, infiltrating primary tumor tissues while all gastric cancer cells or cells adjacent to gastric mucosa did not express S100A9." (PMID 27600085, 2016). "Consistent with the results of immunohistochemistry, S100A8/A9 was not expressed in any cells of gastric cancer tissues, while expression of S100A8/A9 partly overlapped with the S100A9 in inflammatory cells of gastritis tissues." (PMID 22838504, 2012). "Next, we further examined the expression of S100A8, a close family member of S100A9 and the heterodimerization form S100A8/A9 in both gastric cancer tissues and adjacent non-tumor chronic gastritis tissues in the gastric cancer specimens by performing immunohistochemistry." (PMID 22838504, 2012).
glioma (17 papers, 2013 to 2025). A benign or malignant brain and spinal cord tumor that arises from glial cells (astrocytes, oligodendrocytes, ependymal cells). "According to this idea, gliomas could be classified according to a hypoxic inflammation linked with S100A9 expression, a perivascular inflammation related to S100A11 expression, and a microglial inflammation associated to S100A13 expression." (PMID 39744679, 2025). "In addition, S100A8 and S100A9 are associated with progression and prognosis in glioma." (PMID 36046652, 2022). "The amount of S100A9 in the blood of glioma patients was also increased, which can be regarded as a prognostic biomarker of glioma." (PMID 39137310, 2024). "Meanwhile, the expression of S100A9 was also found to increase in glioma stem cells and promoted their proliferation." (PMID 39137310, 2024). "The high expression of S100A9 and S100A8, pro-inflammatory proteins, is associated with poor prognosis in patients with different types of cancer, including glioma or leukemia." (PMID 36552040, 2022). "Altogether, S100A8 and S100A9 play a significant role in proliferation, invasion, migration as well as glioma stem cell stemness via multiple target proteins and signal pathways." (PMID 36046652, 2022). "High expression of S100A8 and S100A9 in glioma inhibits T cell function and their differentiation via interferon-alpha (INF-α) to regulate production of macrophages or dendritic cells." (PMID 34148033, 2021). "S100A3, S100A4, S100A8, and S100A9 expression was up-regulated during the progression of glioma grade." (PMID 34148033, 2021). "S100A8/S100A9 are also implicated in the activation of the NLRP3 inflammasome, which has been shown to play a role in glioma progression." (PMID 34975408, 2021). "RAGE interactions with S100B and S100A9 are well characterized within glioma, but in addition to these two proteins, 11 other S100 members have also been demonstrated to interact with RAGE." (PMID 34975408, 2021). "The results showed that TRIM38, CCR5, PLAU, P2RY8, and PROS1 have a higher immunoreaction score (IRS) in tumors than normal tissues (p < 0.05), while the IRS of HAMP and S100A9 in gliomas were lower than normal tissues (p < 0.05)." (PMID 34954691, 2021). "The significance of high levels of S100A8 and S100A9 in glioma biology was established by performing in vitro functional assays." (PMID 30808902, 2019). "In vitro experiments showed that recombinant S100A8/S100A9 proteins promoted integrin signalling dependent glioma cell migration and invasion up to a threshold level of concentrations." (PMID 30808902, 2019). "To investigate the functional role of S100A8 and S100A9 in GBM microenvironment, we studied the effect of recombinant S100A8 and S100A9 on various proprieties of glioma cells." (PMID 30808902, 2019). "S100A9 was also shown to promote glioma growth and angiogenesis by interaction with the RAGE receptor on the surface of glioma cells, a process mediated via activation of MAPK and NF-κB pathways." (PMID 30323894, 2018). "Leveraging glioma single-cell sequencing data, we identified a novel pro-tumor macrophage subgroup, marked by S100A9, which might interact with endothelial cells to facilitate tumor progression via angiogenesis." (PMID 39136841, 2024). "In addition, the analysis of two sets of gliomas scRNA-seq data illustrated that S100A9 was mainly expressed in monocytes and macrophages." (PMID 39137310, 2024). "S100A8, S100A9 and S100B were highly expression in serum and may present as a marker correlated with survival and prognosis of glioma patients." (PMID 36046652, 2022). "Notably, the transcript levels of S100A8 and S100A9 were found to be significantly up-regulated in GBM tumors as compared to lower grade glioma and control brain tissue in multiple datasets and our cohort." (PMID 30808902, 2019).
glioma (continued). "Specifically, S100A8 and S100A9 were expressed in myeloid cells, S100A10 and S100A11 in various cell types, especially in glioma tumor cells, and S100A13 and S100A16 in vascular cells." (PMID 39744679, 2025). "Pathway communication analysis by CellChat revealed S100A9 Ma’s interactions with other cell types, engaging in the EGF pathway with glioma cells and the VEGF pathway with endothelial cells." (PMID 39136841, 2024). "In gliomas, a high expression of S100A8 and S100A9 inhibits T cell function and differentiation through interferon alpha to regulate macrophage or dendritic cell production." (PMID 37370678, 2023). "TRIM38, CCR5, PLAU, P2RY8, and PROS1 were upregulated in glioma tissues, while HAMP and S100A9 were downregulated." (PMID 34954691, 2021). "Activation of NLRP3 expression by S100A8/S100A9 inhuman PBMCs increased the secretion of pro-inflammatory cytokines (IL-6, IL-1β, TNFα) and chemokines (IL-8, Gro-α, MIP-1α/β) that are prevalent in gliomas." (PMID 34975408, 2021). "Further research into the interactions between S100A8/S100A9, NLRP3, and common inflammatory cytokines may provide potential therapeutic targets for gliomas." (PMID 34975408, 2021). "We found S100A8 and S100A9 failed to induce glioma cell migration and invasion in cells treated with integrin inhibitory peptides (RGD)." (PMID 30808902, 2019). "Similarly, S100A8 and S100A9 proteins induced migration and invasion of U138 glioma cells at a medium, but not at a higher concentration." (PMID 30808902, 2019).
idiopathic pulmonary fibrosis (17 papers, 2015 to 2025). Idiopathic pulmonary fibrosis (IPF) is a nonneoplastic pulmonary disease that is characterized by the formation of scar tissue within the lungs in the absence of any known cause. "Higher proportion of S100A9+CD163– cells among CD14+CD16– MNs was found to be associated with lung fibrosis." (PMID 37561593, 2023). "Thus, S100A8 and S100A9 are associated with lung damage and pulmonary fibrosis by PQ poisoning, and then the mechanism and the potential roles of S100A8 and S100A9 in PQ poisoning require urgent clarification." (PMID 35540476, 2018). "Serum S100A8/S100A9 levels were increased in patients with idiopathic pulmonary fibrosis and acute exacerbation of COPD compared with normal subjects, and negatively associated with pulmonary function." (PMID 39516272, 2025). "S100A9 expression was increased in the lungs of mice, particularly in inflammatory cells and the fibrotic interstitium, in a bleomycin-induced pulmonary fibrosis model." (PMID 40861440, 2025). "S100A9 was not only identified as a marker for idiopathic pulmonary fibrosis, but also aggravated dermal fibrosis induced by bleomycin in mice via activation of ERK1/2 MAPK and NF-κB pathways." (PMID 35784691, 2022). "The positive effect of targeting S100A9 has been observed in many chronic inflammatory diseases with abnormal tissue repair, such as pulmonary fibrosis, renal fibrosis, atherogenesis, and systemic sclerosis phenotype." (PMID 34764959, 2021). "Meanwhile, to evaluate the relationship of S100A8 and S100A9 with PQ-induced pulmonary fibrosis, immunohistochemical (IHC) analysis confirmed the increased expression of these proteins in lung tissue from a rat model of PQ poisoning." (PMID 35540476, 2018). "Furthermore, the authors found unusual levels of certain genes in the red module associated with idiopathic pulmonary fibrosis, specifically S100A12, S100A9, CLEC4E, CRIP1, and IL1R2." (PMID 40782499, 2025). "S100A8 and S100A9 are upregulated in the acute exacerbations of idiopathic pulmonary fibrosis (IPF) suggesting roles of different signaling pathways like Clathrin-mediated endocytosis signaling, atherosclerosis signaling, and IL2 signaling in the pathogenesis of acute exacerbations of IPF." (PMID 34239729, 2021). "Pulmonary fibrosis in the lung tissue of PQ-treated rat was associated with interstitial inflammation and accumulated collagen synthesis, as well as a significant increase in the expression of S100A8 and S100A9." (PMID 35540476, 2018). "Interestingly, the present findings indicate that the expression of DEmRNA S100A12 and S100A9 in the green module related to interstitial pulmonary fibrosis was abnormal, S100A9 expression was reduced in T/NKT cells and B-cells, while S100A12 expression was increased in monocytes." (PMID 40782499, 2025). "We show that EREG expression is induced by type I interferon and co-expressed with alarmins S100A8 AND S100A9, which aligns our findings to previous clinical studies that associated circulating levels of type I interferon and S100A8/A9 with severity of SSc skin and lung fibrosis." (PMID 36490328, 2022). "In Idiopathic pulmonary fibrosis (IPF), elevated level of S100A9 was observed in bronchoalveolar lavage fluid (BALF)." (PMID 32680574, 2020). "In patients with idiopathic pulmonary fibrosis, BALF S100A9 levels were positively correlated with both the number and percentage of neutrophils." (PMID 40861440, 2025). "In comparison to the neutrophilic cases, the IPA analysis of the proteomic datasets derived from horses with metachromatic inflammation revealed enrichment in pathways related to hypersensitivity reaction (CD44, ICAM1, SOD1, PSAP, CDH1) and lung fibrosis (AGER, TGFBR2, FBLN1, S100A9)." (PMID 39594673, 2024).